SLC26A1 (solute carrier family 26 member 1)
Description:
Sodium-independent sulfate anion transporter. Can transport other anions including bicarbonate, thiosulfate and oxalate by mediating sulfate-thiosulfate, sulfate-hydrogencarbonate and sulfate-oxalate anion exchange. Mediates oxalate-hydrogencarbonate anion exchange (By similarity).
Synonyms: SAT-1; SAT1; EDM4; CAON; CAON1; HYSULF
Tractability: Antibody: its Gene Ontology location is reachable by antibodies, with high confidence; UniProt places it where antibodies can reach, with medium confidence; UniProt predicts a signal peptide or a membrane-spanning region.
Gene: Protein-coding gene on chromosome 4 (979,073 to 997,659, reverse strand). Ensembl gene ENSG00000145217.
Subcellular location: Cell membrane; Basolateral cell membrane
Subcellular location (Human Protein Atlas): Microtubules
Pathways (Reactome):
Metabolism: Transport and metabolism of PAPS
Transport of small molecules: Inorganic anion exchange by SLC26 transporters
Gene Ontology:
Molecular function: solute:inorganic anion antiporter activity; chloride transmembrane transporter activity; chloride:bicarbonate antiporter activity; oxalate transmembrane transporter activity; sulfate transmembrane transporter activity; sulfate:bicarbonate antiporter activity; secondary active sulfate transmembrane transporter activity
Biological process: chloride transmembrane transport; chloride transport; oxalate transport; sulfate transmembrane transport; bicarbonate transport; transmembrane transport
Cellular component: basolateral plasma membrane; membrane; plasma membrane
Genetic constraint (gnomAD): Loss-of-function variants: 18 observed, 13.53 expected, observed/expected ratio (o/e) 1.33, 90% interval 0.91 to 1.85. The upper end of that interval is the gene's LOEUF score, 1.85, which puts it in group 6 of 6, group 1 being the genes least tolerant of losing a copy. Missense variants: 1,049 observed, 921.2 expected, observed/expected ratio (o/e) 1.14, 90% interval 1.08 to 1.2. Synonymous variants: 505 observed, 436.86 expected, observed/expected ratio (o/e) 1.16, 90% interval 1.07 to 1.24.
Homologues: Orthologues: chimpanzee SLC26A1 (98% identical), macaque SLC26A1 (95% identical), dog SLC26A1 (81% identical), guinea pig SLC26A1 (80% identical), pig SLC26A1 (80% identical), mouse Slc26a1 (79% identical), rat Slc26a1 (78% identical), tropical clawed frog slc26a1 (53% identical), zebrafish slc26a1 (49% identical). Paralogues in human: SLC26A2 (46% identical), SLC26A6 (33% identical), SLC26A5 (32% identical), SLC26A4 (31% identical), SLC26A3 (30% identical), SLC26A9 (29% identical), SLC26A7 (25% identical), SLC26A8 (24% identical), SLC26A11 (23% identical).
Diseases named in the same sentence as SLC26A1 in open-access papers:
SLC26A1 is named in the same sentence as 31 diseases in open-access papers, as found by Europe PMC text mining. Sharing a sentence is not in itself a finding about the gene and the disease. The quoted sentences say what the papers report.
Hyperoxaluria (6 papers, 2015 to 2025). Increased excretion of oxalates in the urine. "SLC26A1 deletion alters the dynamic balance between oxalate and sulfate, causing hyperoxalemia and consequent hyperoxaluria, renal calcium deposits, and CaOx urolithiasis, and may also predispose to acetaminophen-induced hepatotoxicity." (PMID 37304821, 2023). "In Slc26a1-knockout mice, hyposulfatemia and hypersulfaturia have been reported, whereas the impact of Slc26a1 on oxalate homeostasis leading to hyperoxaluria and urolithiasis remains controversial." (PMID 36719378, 2023). "Both hyperoxaluric and non-hyperoxaluric patients were screened for sequence variations in known and candidate genes implicated in hyperoxaluria (AGXT, GRHPR, HOGA1, SLC26A1, SLC26A6, SLC26A7) by targeted next generation sequencing (tNGS)." (PMID 37270618, 2023). "This is likely due to expression of SLC26A1 in the distal ileum, cecum, and proximal colon in humans, as disruption of basolateral Ox2− transporter in those organs leads to retention of oxalate, hyperoxaluria, and ultimately hyperoxaluria." (PMID 40356774, 2025). "To evaluate the contribution of genetic factors in the development of hyperoxaluria after bariatric surgery, we conducted tNGS to detect variations within genes known to cause monogenic hyperoxaluria and Ca-Ox-NL (AGXT, GRHPR, HOGA1; SLC26A1) as well as the candidate genes SLC26A6 and SLC26A7." (PMID 37270618, 2023). "Here we used the existing rat model of experimental hyperoxaluria, in which female and male animals are treated with an oxalate precursor, ethylene glycol (EG) in order to test if this pathophysiological condition changes protein expression of hepatic and renal oxalate transporter sat-1 (Slc26a1)." (PMID 26526882, 2015). "However, SLC26A1 (localised at the basolateral membrane of the ileum and colon) does not appear to play any significant role in oxalate homeostasis, as SLC26A1 null mice do not exhibit hyperoxaluria or hyperoxalemia." (PMID 40318213, 2025).
Calcium oxalate nephrolithiasis (5 papers, 2013 to 2025). The presence of calcium- and oxalate-containing calculi (stones) in the kidneys. "Mutations in human SLC26A1 which decrease transporter activity and impair membrane trafficking are associated with calcium oxalate nephrolithiasis." (PMID 40356774, 2025). "Gee and colleagues detected biallelic mutations in SLC26A1 in 2 unrelated individuals with calcium oxalate kidney stones, in whom urine oxalate was normal to mildly elevated." (PMID 36719378, 2023). "This study provides preliminary and as yet unreported evidence of sequence variants in the human SLC26A1 gene of a small number of individuals with recurrent calcium oxalate kidney stones." (PMID 24250268, 2013). "Similarly, a dominant negative mutation in SLC26A6 and loss-of-function mutations in SLC26A1 are proposed to cause calcium oxalate nephrolithiasis in humans." (PMID 40991662, 2025). "Human SAT1 (SLC26A1) mutations are associated with calcium oxalate nephrolithiasis." (PMID 40356774, 2025). "Biallelic mutations of SLC26A1 were described in 2 patients with calcium oxalate nephrolithiasis, but the impact on sulfate balance was not assessed." (PMID 36719378, 2023). "Additionally, SLC26A1 has been suggested to play a role in humans with recurrent calcium oxalate kidney stones." (PMID 27412988, 2016).
kidney stone (3 papers, 2013 to 2023). "Thus, the data presented allow SLC26A1 to remain a potential risk factor for nephrolithiasis." (PMID 36719378, 2023). "The novelty of these findings warrants further studies of SLC26A1 in humans with unexplained recurrent kidney stones." (PMID 24250268, 2013). "In the GCKD study, heterozygous carriers of potentially damaging SLC26A1 variants did not have a higher prevalence of self-reported kidney stones compared to noncarriers (P > 0.1)." (PMID 36719378, 2023).
nephrocalcinosis (3 papers, 2013 to 2024). Nephrocalcinosis is a disorder that occurs when too much calcium is deposited in the kidneys. "Our findings of three nonsynonymous gene variants in SLC26A1, including a missense variant at a highly conserved residue in one patient with severe nephrocalcinosis, warrant wider independent studies of SLC26A1 in recurrent calcium oxalate stone formers." (PMID 24250268, 2013).
urolithiasis (3 papers, 2013 to 2023). Stone(s) within the urinary tract. "The correlation between biallelic deleterious variants of SLC26A1 and potential clinical features (urolithiasis and/or cartilage or bone disorders) deserves further clarification." (PMID 36719378, 2023). "To investigate the possible involvement of SAT1 in human urolithiasis, we screened the SLC26A1 gene in a cohort of 13 individuals with recurrent calcium oxalate urolithiasis, which is the commonest type." (PMID 24250268, 2013).
Diarrhea (1 paper, 2025). Abnormally increased frequency (usually defined as three or more) loose or watery bowel movements a day. "CEAS/CNSU caused by SLCO2A1 defects, as well as congenital/familial diarrhea associated with SLC26A1, SLC9A3, and GUCY2C mutations, were the most prevalent monogenic disorders in patients with LO-mIBD, significantly more common than in those with IO-mIBD (p < 0.001)." (PMID 40474095, 2025).
hypersulfaturia (1 paper, 2023). "A role of the anion transporter SLC26A1 (Sat1) for sulfate reabsorption in the kidney is supported by the observation of hyposulfatemia and hypersulfaturia in Slc26a1-knockout mice." (PMID 36719378, 2023).
Infertility (1 paper, 2023). "However, no studies on the role of Slc26a1 in mouse fertility and no human infertility caused by SLC26A1 mutation have been reported." (PMID 38111663, 2023).
intervertebral disc disorder (1 paper, 2023). "In view of recent evidence linking sulfate homeostasis with back pain and intervertebral disc disorder, our study identifies SLC26A1 as a potential target for modulation of musculoskeletal health." (PMID 36719378, 2023). "In view of recent evidence linking sulfate homeostasis to back pain and intervertebral disc disorder, our study identifies SLC26A1 as a potential target for modulation of musculoskeletal health." (PMID 36719378, 2023).
lung adenocarcinoma (1 paper, 2024). A carcinoma that arises from the lung and is characterized by the presence of malignant glandular epithelial cells. "TCGA and GTEx database results showed significant differences in the expression of enzymes and transporters related to oxalate metabolism (LDHA, GRHPR, AGT, DAO, HAO2 and SLC26A1) in tumor tissues of lung adenocarcinoma patients." (PMID 38567154, 2024).
lung carcinoma (1 paper, 2022). "Gene expression of both SLC4A1and SLC26A1 was confirmed in lung epithelial, mesothelial, lung carcinoma,and mesothelioma cells by qPCR." (PMID 36410050, 2022).
male infertility (1 paper, 2023). The inability of the male to effect fertilization of an ovum after a specified period of unprotected intercourse. "Our results exclude SLC26A1 as a contraceptive target and male infertility factor and will help avoid duplication of effort by researchers and save time and money in other laboratories." (PMID 38111663, 2023).
prostate carcinoma (1 paper, 2025). A carcinoma that arises from epithelial cells of the prostate gland. "C4orf48 and SLC26A1 exhibited higher expression in prostate cancer cells compared to normal cells." (PMID 40535819, 2025).
cancer (2 papers, 2022 to 2025). A tumor composed of atypical neoplastic, often pleomorphic cells that invade other tissues. "The expression of the anion transporter proteinsSLC4A1 and SLC26A1 in cells of typical asbestos-burdened tissues andasbestos-related cancers suggests that leached Cr(VI) can readilybe taken up into their intracellular compartment." (PMID 36410050, 2022).
musculoskeletal disorders (1 paper, 2025). "We further investigated the association between the same six functional, sulfate-associated QVs in SLC13A1 and SLC26A1 and musculoskeletal disorders, fractures and injuries in the UKB, for which at least two carriers with and without disease were present." (PMID 39747595, 2025).
neurological disorders (1 paper, 2025). "SLC26A1 and SLC13A1 are two sulfate transporters that have been implicated in sulfate homeostasis and neurological disorders." (PMID 40869915, 2025).
SLC26A1 also shares sentences with these, for which no sentence is quoted: asthenozoospermia (1 paper); bone disorder (1); bronchiectasis (1); calcium oxalate urolithiasis (1); chronic kidney disease (1); Congenital chloride diarrhea (1); deafness (1); developmental delay (1); diastrophic dysplasia (1); hypothyroidism (1); mesothelioma (1); metabolic syndrome (1); multiple epiphyseal dysplasia (1); osteochondrodysplasia (1); tumor (1).